EPO (erythropoietin)
Diseases named in the same sentence as EPO in open-access papers (continued):
Sharing a sentence is not in itself a finding about the gene and the disease.
anemia (continued). "Our second patient with HBSS disease and ESRD received multiple transfusions for symptomatic anemia not responding to erythropoietin." (PMID 27579039, 2016). "Contemporary studies conducted in hemodialysis patients with less severe anemia, most of whom were receiving treatment with erythropoietin, have not found a strong relation between anemia and cognitive function." (PMID 26823182, 2016). "A report has demonstrated circulating autoantibodies against endogenous erythropoietin in some HIV-infected patients due to molecular mimicry between erythropoietin and the HIV-1 p17 protein blunting the normal physiologic cytokine response to anaemia." (PMID 26989408, 2016). "Ruxolitinib inhibits normal erythropoietin and thrombopoietin signaling through JAK2 (through the erythropoietin and thrombopoietin receptors, respectively), often resulting in dose-dependent anemia and thrombocytopenia." (PMID 27017614, 2016). "Therefore, we think that EPO is still required to enhance erythropoiesis in LC-06-JCK mice, although MR16-1 treatment improved anemia status." (PMID 27068103, 2016). "Moreover, Erythropoietin (Epo), the upstream activation factor of the JAK/STAT signaling pathway, is administered as therapeutic agent for treatment of cancer related anaemia." (PMID 27447730, 2016). "The results shown in the present study demonstrate that both EPO and exercise are required to restore the normal heart weight in LLC-bearing mice, where anemia is more severe than in the C26 hosts, suggesting an additive and coordinated action of the two treatments." (PMID 26636649, 2015). "In spite of the increased EPO blood levels, circulating reticulocytes did not increase and, therefore, the anemia did not improve." (PMID 25867633, 2015). "The anemia of CKD is commonly attributed to lack of renal erythropoietin release and subsequent impairment of erythropoiesis." (PMID 25821808, 2015). "Recombinant human erythropoietin (rhEPO), with supplement of other iron agents (such as dextran), is used to promote erythropoiesis and eliminate the iron utilization obstacle for the RBC thrombocytopenia and anemia." (PMID 25802542, 2015). "Finally, in the context of tumor hypoxia, the wide use of rhEPO to treat anaemia in cancer patients, especially ccRCC, is still being discussed because of HIF-induced EPO and EPOR overexpression." (PMID 26210994, 2015). "EPO levels are low in the absence of anemia, but increase dramatically in cases of hypoxic stress due to decreased blood cell mass." (PMID 26575645, 2015). "In chronic inflammation, the compensatory increase in erythropoietin is not commensurate with the severity of anemia." (PMID 26261697, 2015). "RBV dose was not decreased in any patient and erythropoietin was used in 2 (9.5%) individuals because of anemia." (PMID 26640956, 2015). "In ACD and anemia of CKD, alterations of EPO-related mechanisms are discussed, e.g. “relative EPO deficiency”, that is inappropriately low levels of EPO (however, within a “normal range” in a non-anemic reference population) despite low hemoglobin levels." (PMID 25894587, 2015). "We feel reasonably comfortable that anemia is not the driving force behind elevated EPO concentrations in the blood." (PMID 25793991, 2015). "Diseased kidneys do not release sufficient amounts of erythropoietin hormone; anemia can result and it is universal in end-stage renal disease (ESRD)." (PMID 24448756, 2014). "The importance of EPO signaling through its cognate receptor was demonstrated by the identical phenotype of EPO-null and EPOR-null mice: fetal death at embryonic day 13.5 (E13.5) associated with severe anemia and the complete lack of definitive RBCs." (PMID 24478716, 2014). "The activation of erythropoietin (EPO) synthesis as a physiological response to anemia and its relation to a genetic variation within the EPO gene has not been evaluated yet." (PMID 25227310, 2014).
anemia (continued). "This type of anaemia develops due to a chronic inflammatory reaction, characterized by increased concentrations of TNF-α, IL-1, or IFN-gamma, which inhibit the secretion of erythropoietin and availability of iron, essential for efficient erythropoiesis." (PMID 24692849, 2014). "On the other hand, other researchers believe that endogenous erythropoietin level does not significantly reduce anemia in these children, rather bone marrow response to erythropoietin is relatively reduced." (PMID 25598955, 2014). "Anemia is a frequent complication of chronic kidney disease (CKD) because failing kidneys produce insufficient EPO to maintain normal red blood cell levels and hepatic EPO production cannot compensate." (PMID 25392999, 2014). "A small but significant increase in kidney EPO mRNA expression, interpreted as anemia-reactive, was not sufficient to counteract the inflammation-induced anemia in PG-PS-challenged animals." (PMID 25392999, 2014). "There are a few studies on positive effects of human erythropoietin in the treatment of cisplatin-induced anemia compared to regimens without cisplatin." (PMID 25598955, 2014). "Hepcidin is induced by inflammatory cytokines and contributes to the pathogenesis of the so-called anemia of chronic disease (ACD), which is characterized by impaired iron utilization, along with inadequate EPO production, and cytokine-induced inhibition of erythroid precursors." (PMID 24795637, 2014). "Despite the irreplaceable effects of EPO or DA on anemia management in patients with CKD,1–3,7–9 recent large-scale randomized controlled trials strongly suggested harmful effects of higher doses of EPO or DA per se as well as higher Hb levels close to normal (>13 g/dL)." (PMID 24384988, 2013). "EPO administration is the well known medical treatment to enhance erythropoiesis in renal anemia, anemia of prematurity, and anemia with non-myeloid malignancies." (PMID 23977125, 2013). "Therefore, in the current study, the EPO levels of patients with CHF were determined in order to explore the correlation between EPO expression and the severity of CHF and CHF complicated with anemia." (PMID 24223667, 2013). "The EPO expression levels were elevated in CHF patients and patients with CHF and anemia." (PMID 24223667, 2013). "In 2003, Henke and his colleagues pointed out EPO was prosperous to correct anemia in head-and-neck cancer patients; however, it failed to improve, and even impair, cancer patient-sufferers." (PMID 23825635, 2013). "Despite extensive studies in this category, still we do not sure about the effects of erythropoietin and anemia correction on the glomerular filtration rate." (PMID 25340147, 2013). "EPO is best known for its regulatory role in the production of red blood cells, and is widely used to treat anemia resulting from chronic renal failure, AIDS, rheumatoid arthritis, malignancies and many other types of anemia." (PMID 24124563, 2013). "Deletion of HIF-2α, but not HIF-1α, in adult mice gives rise to anemia, indicating its requirement for EPO regulation in physiologic and stress conditions." (PMID 22567318, 2012). "In contrast, knockdown of HIF-2α in astrocytes abrogated hypoxic induction of EPO, consistent with the specificity of HIF-2α in EPO regulation, which was also indicated by the postnatal targeted deletion of HIF-2α in mice leading to anemia." (PMID 22567318, 2012). "In addition to their role in the primary treatment of anaemia of CKD, androgens such as nandrolone have been used as adjuvants to the treatment of anaemia of CKD and for the treatment of erythropoietin-resistant anaemia." (PMID 23119160, 2012). "There is also a blunted response to erythropoietin secretion in sickle cell anaemia; the rate of increase is not proportional to the degree of anaemia." (PMID 22849350, 2012).
anemia (continued). "Thirty four patients who developed anaemia (Hb level ≤ 11 g/dL) among the 319 (11%) GIST patients treated with imatinib in clinical trials or with compassionate use in the 4 French centres, between July 2001 and August 2003, received EPO therapy." (PMID 22950685, 2012). "However, in acute infection of cattle with T. congolense, a compensatory induction of EPO in the kidney and of EPOR in the bone marrow as a feedback response to pathogen-induced anemia has been noted." (PMID 22094132, 2012). "Although our study shows that mild anaemia is associated with increased mortality, randomised trials using erythropoietin in other conditions have shown that complete correction of anaemia is not beneficial." (PMID 21655315, 2011). "In 1991, 117 patients with anemia related to chronic renal failure not yet requiring dialysis were randomized to receive erythropoietin to correct anemia (hematocrit of 40% for males, 35% for females) versus placebo." (PMID 21541213, 2011). "On the other hand, EPOR is highly expressed in the developing mouse brain, and mice lacking EPO or EPOR experienced increased apoptosis in the brain before they died of severe anemia in the uterus." (PMID 22216265, 2011). "Pure red cell aplasia is a rare adverse event, which is characterized by anemia, low reticulocyte count, absence of erythroblasts, resistance to EPO, and neutralizing antibodies against EPO." (PMID 21906325, 2011). "Furthermore, when comparing EPO levels among SMA, CM and MSM, highest values of EPO were found among children with only severe anemia." (PMID 21912616, 2011). "Ablation of ERK1 induces a splenic stress erythropoiesis phenotype, but the mice display no anemia and did not affect EPO levels or EPO/EPO receptor signaling." (PMID 21206920, 2010). "Established treatment options for anemia of chronic kidney disease (CKD) are Erythropoietin Stimulating Agents (ESA), including erythropoietins (EPO alfa, beta), darbepoetin (DARBO α), pegylated epoietin (continuous erythropoietin receptor activator, CERA) and biosimilar epoetins." (PMID 20534124, 2010). "This indicates that, also in humans, neither hypoxia nor anemia are required for the suppression of hepcidin by erythropoiesis and challenges the idea that erythropoietin induction and hepcidin inhibition are parallel effects of HIF activation." (PMID 19924283, 2009). "We will then focus on molecular regulation of erythroid differentiation rather than on iron or erythropoietin involvement in anemia." (PMID 20204172, 2009). "In P. chabaudi (AS) infections, impaired erythropoiesis has been shown to be due, in part, to the reduced ability of RBC precursors to respond to erythropoietin (EPO), resulting in limited replacement of RBCs and thus exacerbation of anaemia observed during infection." (PMID 18439291, 2008). "Because the peritubular cells are not exposed to local hypoxia, the stimulus to increase erythropoietin production is absent and anemia and peripheral hypoxia go uncorrected." (PMID 17910755, 2007). "Correcting anemia with transfusions and application of erythropoietin therefore seems to be a valid approach to compensate for the negative effects of anemia." (PMID 17150114, 2006). "Only anaemia has a grade II severity level more costly to manage than the other grades due to the use of erythropoietin, whereas grades III and IV were considered to be treated with transfusions, which are less costly than erythropoietin." (PMID 12966416, 2003). "Interstitial fibrosis (IF), which disrupts the renal interstitium where erythropoietin-producing cells reside, may contribute to anemia independent of glomerular filtration rate (GFR)." (PMID 42195073, 2026). "Mice lacking EPO or EPOR die mid-gestation due to severe anemia." (PMID 39996752, 2025). "Horses may develop antibodies neutralizing both exogenous and endogenous EPO, leading to non-regenerative anemia and long-term complications, making EPO use both ineffective and hazardous." (PMID 40565115, 2025).
anemia (continued). "Further investigation into the pathophysiological pathways linking inflammation and erythropoietin resistance—particularly those related to the malnutrition–inflammation complex and PEW syndrome—may provide new therapeutic targets to optimize anemia control in this vulnerable population." (PMID 40429405, 2025). "Consequently, the role of the ERFE–hepcidin–EPO axis in the pathophysiology of CKD-related anemia has not been fully elucidated." (PMID 41227183, 2025). "Mice lacking EPO or its receptor (EPOR) die in utero due to severe anemia." (PMID 39996752, 2025). "Moreover, treatment with erythropoietin derivatives increases cardiovascular complications, and therefore is subject to limits that do not allow complete reversal of anemia." (PMID 40773297, 2025). "Although no direct association was identified between the EPO polymorphism and ROP (distant phenotype), the polymorphism influenced some hematological parameters related to anemia and thrombocytopenia (intermediate phenotypes), both recognized as potential risk factors for ROP." (PMID 39940677, 2025). "However, in human studies, to assess the benefit on the cardiovascular health of long-term high-dose EPO treatment for anemia in chronic kidney disease, no benefit to heart health was found." (PMID 38628440, 2024). "Notably, the coexistence of anemia and decreased serum EPO concentration, independent of kidney damage, has been observed in many HIV patients." (PMID 38675885, 2024). "Although erythropoietin stimulating agents (ESAs) were considered a rational therapy to increase hemoglobin and to treat anemia in CKD patients with HF, these agents do not improve outcomes and may be associated with thromboembolic complications." (PMID 39685694, 2024). "Because the mechanisms that explain inter-individual variation in the improvement of anemia-associated CKD have still not been clarified, the present research aimed to determine correlations between circulating EPO, ERFE, and EP-25 serum levels and the effectiveness of erythropoiesis in ESRD." (PMID 39179496, 2024). "The observation made in the JAXA cohort seems to be in congruence with the observed phenotype of space anaemia, suggesting that the down-regulation of EPO in flight, as observed for the JAXA astronauts, might have had a negative effect on erythropoiesis and thus contributed to space anaemia." (PMID 38862545, 2024). "Concentrations of two major niche factors, SCF and CXCL1237–40, were higher in the BM fluid than those in the blood plasma but did not increase upon anemia induction, indicating that proliferation and altered lineage-choice were not due to the effect of EPO or SCF/CXCL12." (PMID 39284836, 2024). "However, transfusion independence responses with momelotinib were observed regardless of baseline EPO level, suggesting that this criterion should not impact consideration of momelotinib in patients who require an anemia benefit." (PMID 38990433, 2024). "Currently, therapeutic strategies for renal anemia focus on correcting anemia itself through the use of erythropoiesis-stimulating agents, recombinant human EPO, and inhibitors of prolyl-hydroxylase-HIF, which are used primarily to increase EPO levels and stimulate erythropoiesis." (PMID 39845803, 2024). "Additionally, levels of erythropoietin (EPO) in the peripheral blood serum of Vav1-Cre/Shmt2fl/fl mice were significantly elevated compared to those in control animals, indicating a compensatory response to the anemia." (PMID 39456851, 2024). "Therefore, the focus is on the concentration of EPO in relation to other anemia markers rather than on the exact prevailing EPO concentration." (PMID 38974321, 2024). "Although chronic anemia in PLWH may contribute to the development of CKD, more often than not, anemia mostly occurs in the context of CKD due to the reduced production of erythropoietin and is worsened as CKD progresses." (PMID 38675885, 2024).
anemia (continued). "Data on the rate of blood transfusions in phase III clinical trials are lacking, but we recommend erythrocyte transfusions when anemia provokes asthenia or hemoglobin falls to < 10 g/dL, or erythropoietin administration as a last resort, according to clinical judgement." (PMID 38336982, 2024). "However, in murine anemia during severe malaria (P. berghei infected BALB/c), erythropoietin does not influence anemia onset." (PMID 39492784, 2024). "This underutilization may reflect the current guidelines and practices surrounding EPO, which is generally recommended in specific cases of anemia rather than as a standard treatment for SCD." (PMID 39685683, 2024). "Notably, kidney cancer patients frequently exhibit anemia, with up to 35% of cases demonstrating decreased levels of hemoglobin (HGB), hematocrit (HCT), MCV, and MCH due to the weak activity of erythropoietin (EPO) and abnormal iron metabolism." (PMID 38846978, 2024). "Second, erythropoietin levels were not routinely checked in all patients, which is important in deciding whether the anemia is transient or permanent." (PMID 39460859, 2024). "Besides anemia, recent studies have identified new therapeutic indications for EPO that are not connected to red blood cell formation." (PMID 39278948, 2024). "Inflammation that we detected in mutant mice could be a driver of anemia in CKD, either directly through inhibition of EPO-mediated erythropoiesis or indirectly via disrupted iron regulation that limits hemoglobin synthesis in erythroid cells in the bone marrow." (PMID 38512983, 2024). "As Erfe-/- mice exhibit only mild anemia during the postnatal period, ERFE expression increases post-phlebotomy and in response to exogenous EPO, supporting a hypothesis that its main function is to facilitate iron mobilization during recovery from transient anemia." (PMID 37578340, 2023). "CRF results in metabolic dysfunction characterized by azotemia (elevated blood urea nitrogen (BUN), creatinine, and phosphorus), anorexia, various electrolyte abnormalities, dehydration, and non-regenerative anemia due to inadequate renal erythropoietin production." (PMID 37632117, 2023). "The unexplained anemia cohort (36% of all the anemic population) was found to have higher levels of pro-inflammatory markers and higher resistance of bone marrow erythroid progenitors to erythropoietin compared to non-anemic controls." (PMID 37240288, 2023). "Thus, we analyzed and compared clinical factors, serum inflammatory markers, EPO, and sFas levels from the baseline levels between patients with and without anemia within up to 12 years of follow-up." (PMID 37390095, 2023). "Anemia occurred surprisingly more often in patients without sarcopenia, but this should be interpreted with caution as we were unable to identify patients who underwent a blood transfusion or treatment with erythropoietin-stimulating agents." (PMID 36983212, 2023). "Patients with heart failure may experience brief episodes of hypoxia, which may not sufficiently stimulate the production of EPO, leading to anemia." (PMID 37374094, 2023). "Enhanced erythropoiesis from increased endogenous erythropoietin production and increased tissue oxygen extraction mediated by 2,3-diphosphoglycerate concentrations are the main non-hemodynamic compensatory mechanisms in anemia." (PMID 37840653, 2023). "Recently reported data from a multicenter international study on the efficacy and safety of erythropoietin (EPO) treatment in AIHA revealed that the majority of the 51 included patients had inadequate reticulocytosis and reduced endogenous EPO levels considering the degree of anemia displayed." (PMID 37761258, 2023). "At present, the main treatment of anemia consists of RBC transfusions and several alternatives to blood transfusions, such as preoperative iron and vitamins or folate supplementation, autologous blood donation, or administration of recombinant human erythropoietin." (PMID 37013545, 2023).